SH3RF1 (SH3 domain containing ring finger 1)
Description:
Has E3 ubiquitin-protein ligase activity. In the absence of an external substrate, it can catalyze self-ubiquitination. Stimulates ubiquitination of potassium channel KCNJ1, enhancing its dynamin-dependent and clathrin-independent endocytosis. Acts as a scaffold protein that coordinates with MAPK8IP1/JIP1 in organizing different components of the JNK pathway, including RAC1 or RAC2, MAP3K11/MLK3 or MAP3K7/TAK1, MAP2K7/MKK7, MAPK8/JNK1 and/or MAPK9/JNK2 into a functional multiprotein complex to ensure the effective activation of the JNK signaling pathway. Regulates the differentiation of CD4(+) and CD8(+) T-cells and promotes T-helper 1 (Th1) cell differentiation. Regulates the activation of MAPK8/JNK1 and MAPK9/JNK2 in CD4(+) T-cells and the activation of MAPK8/JNK1 in CD8(+) T-cells. Plays a crucial role in the migration of neocortical neurons in the developing brain. Controls proper cortical neuronal migration and the formation of proximal cytoplasmic dilation in the leading process (PCDLP) in migratory neocortical neurons by regulating the proper localization of activated RAC1 and F-actin assembly (By similarity). (Microbial infection) Plays an essential role in the targeting of HIV-1 Gag to the plasma membrane, this function is dependent on its RING domain, and hence its E3 ligase activity.
Synonyms: KIAA1494; POSH; RNF142; SH3MD2
Tractability: PROTAC: UniProt records ubiquitination sites on it; ubiquitination databases record sites on it; its protein half-life has been measured.
Gene: Protein-coding gene on chromosome 4 (169,094,259 to 169,271,185, reverse strand). Ensembl gene ENSG00000154447.
Subcellular location: Cytoplasm, perinuclear region; Cell projection, lamellipodium; Golgi apparatus, trans-Golgi network
Subcellular location (Human Protein Atlas): Vesicles; Intermediate filaments
Pathways (Reactome):
Immune System: Antigen processing: Ubiquitination & Proteasome degradation
Signal Transduction: RHOV GTPase cycle
Gene Ontology:
Molecular function: protein binding; ubiquitin protein ligase activity; MAP-kinase scaffold activity
Biological process: negative regulation of apoptotic process; negative regulation of extrinsic apoptotic signaling pathway; protein autoubiquitination; neuron migration; positive regulation of JNK cascade; regulation of CD4-positive, alpha-beta T cell differentiation; regulation of CD8-positive, alpha-beta T cell proliferation; MAPK cascade; protein ubiquitination; response to aldosterone
Cellular component: cytosol; lamellipodium; Golgi apparatus; perinuclear region of cytoplasm
Genetic constraint (gnomAD): Loss-of-function variants: 30 observed, 68.53 expected, observed/expected ratio (o/e) 0.44, 90% interval 0.33 to 0.59. The upper end of that interval is the gene's LOEUF score, 0.59, which puts it in group 2 of 6, group 1 being the genes least tolerant of losing a copy. Missense variants: 935 observed, 1,147.2 expected, observed/expected ratio (o/e) 0.82, 90% interval 0.77 to 0.86. Synonymous variants: 389 observed, 449.51 expected, observed/expected ratio (o/e) 0.87, 90% interval 0.8 to 0.94.
Homologues: Orthologues: chimpanzee SH3RF1 (99% identical), macaque SH3RF1 (99% identical), rabbit SH3RF1 (94% identical), guinea pig SH3RF1 (93% identical), dog SH3RF1 (92% identical), mouse Sh3rf1 (91% identical), rat Sh3rf1 (91% identical), pig SH3RF1 (80% identical), tropical clawed frog sh3rf1 (72% identical), zebrafish sh3rf1 (63% identical), Caenorhabditis elegans sorb-1 (15% identical), Caenorhabditis elegans B0303.7 (11% identical), and 1 more. Paralogues in human: SH3RF3 (48% identical), SH3RF2 (27% identical), SORBS1 (15% identical), SORBS2 (13% identical), SORBS3 (12% identical), SH3D19 (10% identical), SH3GLB2 (7% identical), SH3GL1 (7% identical), SH3GL2 (7% identical), SH3GLB1 (7% identical), SH3GL3 (7% identical), NCF4 (6% identical).
Diseases named in the same sentence as SH3RF1 in open-access papers:
SH3RF1 is named in the same sentence as 17 diseases in open-access papers, as found by Europe PMC text mining. Sharing a sentence is not in itself a finding about the gene and the disease. The quoted sentences say what the papers report.
breast carcinoma (3 papers, 2017 to 2025). "However, higher expression of SH3RF1 is related to increased “stemness” properties of breast cancer cells and CAPRIN2 may also play a role in carcinogenesis." (PMID 40837030, 2025). "In the analysis of the correlation between overall survival and significant DEG expression (CLDN7, MLLT10, RBM33, SH3RF1, SSBP4, and UBE2Z) in breast cancer, we found a shorter survival time based on GSE5881 and GSE42568 (P< 0.05)." (PMID 34151730, 2021). "Significantly overexpressed genes (CLDN7, MLLT10, RBM33, SH3RF1, SSBP4, and UBE2Z) were correlated with shorter survival, whereas underexpressed genes (BMPER, FGF7, MSRB3, and TNRC6B) were correlated with longer survival in breast cancer." (PMID 34151730, 2021). "Interestingly, other DEGs in breast cancer identified in this study, including MLLT10, RBM33, SH3RF1, UBE2Z, and TNRC6B, have not been proven in previous studies." (PMID 34151730, 2021).
glioma (1 paper, 2023). A benign or malignant brain and spinal cord tumor that arises from glial cells (astrocytes, oligodendrocytes, ependymal cells). "KALRN, EIF1AD, DLL1, SH3RF1, and TLN1 are involved in neuronal structural integrity, plasticity, differentiation, and may contribute to the highly invasive nature of GBM as compared to other gliomas." (PMID 36834486, 2023).
lung adenocarcinoma (1 paper, 2018). A carcinoma that arises from the lung and is characterized by the presence of malignant glandular epithelial cells. "We can also consider SH3RF1 as a new therapeutic target that can be researched to discover new treatment methods for lung adenocarcinoma patients with the LKB1 mutation." (PMID 30185829, 2018). "However, additional experiments must be performed that will more deeply explore the underlying mechanism of SH3RF1 in LKB1 mutant lung adenocarcinoma." (PMID 30185829, 2018). "Therefore, we can designate SH3RF1 as a new diagnostic biomarker and indicator that can be used to evaluate the survival and prognosis of LKB1 mutant lung adenocarcinoma patients." (PMID 30185829, 2018). "All of these differences might explain why SH3RF1 can affect the prognosis in LKB1 mutant lung adenocarcinoma patients." (PMID 30185829, 2018). "We found that there was great clinical value in the SH3RF1 gene and that it could act as a new diagnostic biomarker and indicator to evaluate survival and prognosis of LKB1 mutant lung adenocarcinoma patients." (PMID 30185829, 2018). "SH3RF1 might have great clinical value act as a diagnostic biomarker and indicator to evaluate the prognosis of LKB1 mutant lung adenocarcinoma patients." (PMID 30185829, 2018). "SH3RF1 can become a new treatment target and help us find new treatment methods for LKB1 mutant lung adenocarcinoma patients." (PMID 30185829, 2018). "There were significantly expressed differences in the ubiquitin-related gene SH3RF1 between the LKB1 mutant and wild-type lung adenocarcinoma patients (p = 9.78013E-05)." (PMID 30185829, 2018).
lung carcinoma (1 paper, 2020). "However, the roles of these POSH members in cancer are unexplored, although dysregulation of SH3RF1 and SH3RF3 has been implicated in lung cancer and leukemia." (PMID 32427938, 2020).
cancer (4 papers, 2011 to 2023). A tumor composed of atypical neoplastic, often pleomorphic cells that invade other tissues. "Moreover, bioinformatic analysis of The Cancer Genome Atlas (TCGA) data revealed a high positive correlation across multiple human cancers between the mRNA level of BIRC6 and SH3RF1, the human orthologs of Bruce and POSH, respectively." (PMID 37699871, 2023).
SH3RF1 also shares sentences with these, for which no sentence is quoted: Cerebral ischemia (2 papers); tumor (2); B-cell acute lymphoblastic leukemia (1); frontotemporal dementia (1); infection (1); intestinal diseases (1); ischemia (1); neurodegenerative disease (1); pancreatic cancer (1); Parkinson disease (1); prostate carcinoma (1); squamous non-small-cell lung carcinoma (1).